INS (insulin)
Diseases named in the same sentence as INS in open-access papers (continued):
Sharing a sentence is not in itself a finding about the gene and the disease.
Obesity (continued). "Conversely, the development of leptin resistance—closely linked to obesity—promotes triglyceride accumulation in adipose tissue, liver, skeletal muscle, and pancreas, leading to impaired insulin secretion, decreased insulin sensitivity, and ultimately, the development of IR." (PMID 41303021, 2025). "Additionally, these agents facilitate weight loss and are recommended for obesity treatment, with improvements in insulin sensitivity observed prior to significant weight reduction." (PMID 40564010, 2025). "Furthermore, oestrogens are involved in the regulation of metabolism, with low oestrogen levels linked to obesity, inflammation, abnormal lipid profiles, and reduced insulin sensitivity." (PMID 40136716, 2025). "However, patients with obesity have a decreased level of adiponectin, causing insulin resistance or reduced insulin sensitivity." (PMID 40863244, 2025). "Additionally, short sleep duration impacts cortisol secretion, resulting in disturbance of the glucose‐insulin metabolism and substrate oxidation and, ultimately, increased risk of obesity." (PMID 40247658, 2025). "Metabolically healthy obesity refers to a subgroup of obese individuals with high BMI associated with a healthy metabolic profile characterized by high insulin sensitivity, a favorable lipid profile and low levels of pro-inflammatory cytokines in plasma and adipose tissue." (PMID 40255500, 2025). "Furthermore, SH2B1—which regulates energy balance through insulin sensitivity and adipocyte function—shows male-specific obesity association at the rs7359397 locus." (PMID 41340654, 2025). "Bioactive glycerolysophospholipids (GLPs) are implicated in the pathogenesis of metabolic dysfunction-associated steatotic liver disease (MASLD) and obesity; however, the mechanisms underlying glycerolysophospholipid-mediated changes in insulin signaling remain poorly understood." (PMID 40760121, 2025). "The purpose of this study was to investigate whether the obesity‐associated increase in insulin‐stimulated BGU is linked to brain inflammation and altered resting‐state brain activity." (PMID 40926735, 2025). "This suggests that high sAA activity may be associated with a rapid insulin response and a swift reduction in blood glucose levels following starch ingestion, which may protect against obesity via improved glucose metabolism and enhanced satiety." (PMID 40871668, 2025). "The hypothesis suggests that tirzepatide's dual GIP and GLP‐1 agonism creates a potent metabolic effect that could be leveraged to treat obesity by promoting fat loss and improving insulin sensitivity." (PMID 39540705, 2025). "IR refers to the reduced ability of insulin target tissues to respond to insulin signaling, promoting compensatory hyperinsulinemia, which is closely associated with MetS and related disorders such as obesity, NAFLD, and hypertension." (PMID 41614828, 2025). "To provide a better insight into the relationship between changes in adiposity and AT pO2, we recently performed an intervention study in humans, showing that diet-induced weight loss decreased AT pO2, which was accompanied by improved insulin sensitivity in humans with overweight/obesity." (PMID 39298040, 2025). "Obesity, which disrupts glucose-insulin metabolism, is associated with decreased SHBG levels." (PMID 40861046, 2025). "Ruminiclostridium 9 has also been shown to regulate lipid metabolism, reduces inflammation, enhances intestinal barrier function, and increases insulin sensitivity, thereby potentially reducing the development of obesity—a known risk factor for pancreatic cancer." (PMID 39906083, 2025). "According to studies, decreasing sleep duration may raise the risk of weight gain and obesity by upregulating hunger also through a drop in leptin, an increase in ghrelin, and a decrease in insulin sensitivity." (PMID 38778593, 2025).
Obesity (continued). "Older individuals and those with obesity have generally favourable exercise-induced adaptations in insulin sensitivity and other cardiometabolic risk factors, but they frequently fail to reach levels seen in younger people, possibly due to body composition differences." (PMID 40127780, 2025). "In the liver, PDGF-AA/PDGFRα signaling integrates matrix remodeling with hepatocyte insulin action; its upregulation in obesity is associated with inflammatory tension and fibrosis, providing a non-cell-autonomous cue that exacerbates hepatic insulin resistance." (PMID 41480360, 2025). "The improved insulin sensitivity observed in mice with whole-body ablation of PI3Kγ was associated with reduced metabolic inflammation and hepatosteatosis; a phenotype that was associated with their protection from diet-induced obesity." (PMID 39811649, 2025). "An early study that categorized GDM into subgroups based on body weight showed that the subgroup of maternal obesity had higher risk of macrosomia than the normal body weight group, while those with normal body weight exhibited deteriorated insulin secretion compared with those with obesity." (PMID 39446494, 2025). "Metabolic syndrome is a prevalent metabolic disorder closely associated with a high incidence of obesity, and its pathophysiological mechanisms predominantly involve insulin resistance, excessive release of free fatty acids, and particularly, a chronic proinflammatory state." (PMID 41169786, 2025). "Insulin levels are considered a serious risk factor for obesity." (PMID 40722558, 2025). "As abnormality in insulin secretion induces obesity, the tendency to gain weight in rs17108108 C allele carriers may be partially explained by altered insulin secretion caused by decreased levels of Ca2+." (PMID 40440257, 2025). "Beyond glucose regulation, asprosin modulates energy metabolism, appetite, insulin secretion, inflammatory responses, apoptotic cell death, and reproductive function, with altered signaling implicated in disorders such as DM, obesity, polycystic ovary syndrome, malignancies, and cardiomyopathies." (PMID 41286678, 2025). "A meta-analysis of 27 randomized controlled trials involving 1278 participants showed that KDs significantly reduce body weight, BMI, triglycerides, blood glucose, insulin, and diastolic blood pressure, suggesting metabolic benefits for obesity and cardiovascular risk." (PMID 40699839, 2025). "Longitudinal studies are needed to determine whether improving vitamin D status can enhance insulin sensitivity and reduce metabolic risk in children with obesity." (PMID 41362334, 2025). "While insulin-sensitive individuals may struggle with low-carbohydrate, high-protein diets, those with insulin resistance or a genetic predisposition to obesity often tolerate such diets well." (PMID 40462791, 2025). "We discuss the association of obesity with sarcopenia (a form of SM atrophy), the metabolic sequelae of sarcopenia (including the key role of the SM in determining insulin sensitivity), and the inherent difficulties of clinical assessment of SM mass and functioning in the context of obesity." (PMID 39997710, 2025). "In men, experimental studies have shown that AR deficiency worsens obesity and glucose intolerance, suggesting that androgens may play a role in modulating insulin sensitivity in men." (PMID 39765884, 2024). "Previously, it was hypothesized that the competition between increased circulating fatty acids and glucose for oxidative metabolism in insulin responsive cells explained the association between obesity and type 2 DM." (PMID 38339160, 2024). "Moreover, skipping breakfast has also been associated with an impaired postprandial insulin response, potentially increasing the risk of obesity by influencing insulin secretion and blood sugar regulation." (PMID 39599620, 2024).
Obesity (continued). "Finally, myr-PrRP20 or palm-PrRP31 was chronically SC injected into DIO mice for 2 weeks; this treatment resulted in significant weight loss and improved metabolic parameters related to obesity, such as decreased leptin or insulin levels." (PMID 38577975, 2024). "Endogenous hyperinsulinemia may cause weight gain and obesity, and treatment with insulin causes substantial weight gain, and may even increase cardiovascular risk." (PMID 38890501, 2024). "The insulin signaling pathway has been put forward as a possible mechanism underlying the association between obesity and CRC, since increased levels of circulating insulin (as seen with increased fat tissue) stimulate colorectal epithelial cell proliferation in rat models." (PMID 39770972, 2024). "It is possible that the association of obesity with treatment with liposomes generated a synergistic effect leading to glucose intolerance and greater difficulty for the animals in this OH group to secrete insulin when faced with a glucose overload." (PMID 39452080, 2024). "As obesity is a risk factor for at least thirteen malignancies such as pancreatic and colon cancer through dysregulation of insulin and hormonal signaling pathways, the incidence of obesity-associated cancers is anticipated to increase concurrently with rising rates of obesity." (PMID 39931650, 2024). "Studies suggest that the MD may contribute to weight control, improved lipid profiles, insulin sensitivity, and endothelial function, thereby reducing the risk of metabolic syndrome in children and adolescents with obesity." (PMID 38732533, 2024). "The algorithm is then applied to learn the causal structure among 51 variables including obesity, early life factors, diet, lifestyle, insulin resistance, puberty stage and cultural background of 5112 children from the European IDEFICS/I.Family cohort across three waves (2007–2014)." (PMID 38514750, 2024). "Specifically, it suggests that higher insulin secretion after formula feeding could contribute to obesity risk." (PMID 39683381, 2024). "Additionally, while 12-HETE decreases insulin secretion in vitro, it is also decreased in obesity and inversely associated with arterial stiffness even after BMI adjustment." (PMID 38826341, 2024). "In obese mice, FGF21 treatment has been shown to notably enhance insulin sensitivity, promote energy expenditure, and augment fat oxidation while also inhibiting de novo lipogenesis in the liver, thereby ameliorating obesity and its associated metabolic complications." (PMID 38673797, 2024). "However, few reports have been published so far assessing the relationship between the rs3842729 polymorphism of the INS with the development of obesity and T2D." (PMID 38250713, 2024). "However, it has been consistently observed that PTEN loss is associated with improved insulin sensitivity in obesity models." (PMID 39095788, 2024). "Therefore, KETO, when managed carefully, contributes to fat breakdown and enhanced insulin signaling, thus counteracting the onset and progression of steatotic liver disease while concomitantly improving associated comorbidities like obesity and T2DM." (PMID 39796579, 2024). "Similarly, arginine and ornithine have been associated with obesity and insulin deficiency, as evidenced in studies comparing obese versus lean individuals and insulin-deficient mouse models." (PMID 39770889, 2024). "Gene markers associated with cardiovascular dysfunction, insulin signaling, and obesity identified in our study may also be regulated by the gut microbiome." (PMID 38153260, 2024). "Our findings strongly indicate a potential pathway of LPS biosynthesis in obesity, with elevated levels of LPS—linked to a high-fat diet—contributing to localized intestinal inflammation, systemic pro-inflammatory cascades, and triggered insulin resistance." (PMID 39200519, 2024).
Obesity (continued). "Moreover, this allele has been found to be positively associated with a lower body mass index and increased insulin sensitivity, as well as a reduced risk of developing obesity." (PMID 39408225, 2024). "This is due to the fact that obesity causes β-cell dysfunction and insulin resistance." (PMID 38892526, 2024). "Mitochondrial dysfunction caused by obesity results in increased reactive oxygen species that can further disrupt insulin-signaling and promote M1 polarization of macrophages and activate the inflammasome, which again leads to disruptions in metabolism and promotes obesity." (PMID 38605957, 2024). "Significantly, among all the plasma amino acids examined individually, glycine exhibited the strongest association with altered insulin sensitivity, thereby mitigating obesity through the facilitation of efficient sugar utilization and reduction of blood glucose levels." (PMID 39070255, 2024). "Obesity is known to be associated with reduced insulin sensitivity." (PMID 39596499, 2024). "Apart from that, insulin plays important role, as in glucose homeostasis, cell growth, and metabolism, and impaired insulin signalling and IR often leads to development of metabolic diseases such as obesity, T2D and classic phenotype of PCOS, all of them associated with infertility." (PMID 39396139, 2024). "Obesity-associated microbiota influences the efficiency of calorie uptake from ingested foods, host energy harvesting, insulin resistance, hepatic metabolism, inflammation, as well as central regulation of appetite and satiety and food reward signalling, which all have crucial roles in obesity." (PMID 38765954, 2024). "Additionally, imbalances of salivary hormones, such as higher levels of insulin and leptin, have been associated with obesity in children, while these hormones, among others, are also involved in taste sensation." (PMID 39203770, 2024). "Subsequently, experiments using the hyperinsulinemic-euglycemic clamp model revealed that V1aR-deficient rats are less sensitive to insulin, whereas V1bR-deficient mice maintained on a high-fat diet manifest impaired glucose tolerance and develop overt obesity." (PMID 39769071, 2024). "We compared concentrations of often reported brain metabolites measured with magnetic resonance spectroscopy (1H-MRS, 3 T MRI) in the occipital lobe in subjects with obesity and lean controls under different metabolic conditions (fasting, insulin clamp, following weight loss)." (PMID 37824728, 2024). "The data indicate that carrageenan acts in synergism with obesity and possibly other factors, such as an altered microbiome, in at-risk individuals to further disrupt the intestinal barrier, exaggerate systemic inflammation, and increase insulin resistance." (PMID 39593091, 2024). "However, the interactions mediate obesity-associated pathways including the inflammatory response, oxidative stress, insulin signaling, gut permeability, and lipogenesis." (PMID 39684547, 2024). "Obesity is typically associated with declining metabolic health, including impaired regulation of glucose homeostasis and metabolism through the action of insulin (insulin resistance)." (PMID 37801203, 2024). "Furthermore, increased homoeostatic model assessment (HOMA-IR) implies that both conplastic strains are predisposed to impaired insulin sensitivity during obesity." (PMID 39261587, 2024). "We sought to determine whether higher serum myostatin levels are independently associated with lower insulin sensitivity in adults with overweight/obesity." (PMID 39261976, 2024). "Some studies suggested that the correlation between obesity and breast cancer may be attributed to systemic and local changes caused by obesity, such as elevated levels of insulin, glucose, and hormones derived from adipose tissue." (PMID 38676834, 2024). "However, the pathophysiology and development of obesity have been linked to the pancreas’ hypersecretion of insulin." (PMID 38397458, 2024).
Obesity (continued). "Notably, ADRA2A rs1800544 was linked to HOMA-IR and postprandial insulin levels, consistent with earlier findings that associated this variant with MetS and obesity." (PMID 39858569, 2024). "In addition, high insulin levels as a result of obesity and/or T2D are associated with decreased SHBG synthesis, resulting in higher unbound and active sex hormones." (PMID 39467940, 2024). "Obesity is associated with a chronic state of adipose tissue inflammation that leads to changes in cytokine secretions by adipocytes and macrophages, thereby resulting in various metabolic dysfunctions, including malfunctions in insulin signaling." (PMID 39768098, 2024). "Obesity may elevate the risk of AD through various mechanisms, including chronic inflammation, impaired brain insulin signaling, vascular damage, and hormonal and neurotransmission changes (e.g., leptin and glutamate)." (PMID 39596023, 2024). "Indeed, this approach improves systemic insulin sensitivity and lowers the risk of developing obesity-related complications." (PMID 39619489, 2024). "Bariatric surgery has been shown to significantly lower the risk of developing obesity-associated cancers, which are linked to metabolic dysregulation, chronic low-grade systemic inflammation, and hormonal alterations such as elevated insulin and sex hormone levels." (PMID 39630839, 2024). "It has been linked to an increased risk of obesity, which may affect the metabolism of insulin and glucose, accelerate leptin production or secretion, and enhance leptin resistance." (PMID 38672736, 2024). "Obesity during pregnancy significantly impacts glucose metabolism, causing impaired fasting glucose regulation in early pregnancy and a pronounced increase in peripheral and hepatic insulin resistance." (PMID 39690358, 2024). "In conclusion, Clcn3 deficiency ameliorates HFD-induced obesity, meanwhile, improves glucolipid metabolism disorders, and the impairment of insulin sensitivity, which may be because of the AMPK-Ucp1 axis." (PMID 38784133, 2024). "Upon a high‐fat diet, long‐lived GHRH‐KO mice retain insulin sensitivity and consistent metabolic rates, contrary to wild‐type mice, indicating growth hormone deficiency may offer protection against obesity‐related metabolic impairment." (PMID 38867381, 2024). "Consumption of either 3 soy, or 3 casein, shakes daily as part of a 16-week, energy-restricted diet, in two groups of women with obesity, had comparable effects on weight loss and body composition, as well as fasting insulin, while a greater reduction in fasting glucose was evident in the soy group." (PMID 39145315, 2024). "For example, caffeine may alter blood glucose levels, insulin sensitivity, and lipid metabolism, and these metabolic changes could exacerbate obesity and chronic inflammation, thereby increasing the risk of BPH." (PMID 39872138, 2024). "However, increased abundance of CAT, together with other proteins related to metabolic pathways has been associated with human AT protection and insulin-stimulated glucose uptake improvements in obesity." (PMID 38703299, 2024). "Recent physiological studies have identified potential mechanisms that influence offspring obesity development due to paternal BMI, including decreased growth hormone causing excess lipid accumulation in adipose tissue and altered glucose-insulin homeostasis due to beta-cell dysfunction." (PMID 38672435, 2024). "Similarly, miR-4431 is another obesity-associated miRNA that has been linked to worsened glucose tolerance and insulin sensitivity." (PMID 39769251, 2024). "Furthermore, obesity is associated with metabolic dysfunctions such as hyperglycemia, dyslipidemia, altered lipid profiles, and reduced insulin sensitivity." (PMID 39796489, 2024). "Some studies suggest that FMT may improve insulin sensitivity, which could aid in managing obesity and type 2 diabetes, which are closely associated with MetS." (PMID 39429422, 2024).